SCN1A (sodium voltage-gated channel alpha subunit 1)
Diseases named in the same sentence as SCN1A in open-access papers (continued):
Sharing a sentence is not in itself a finding about the gene and the disease.
epilepsy (continued). "SCN1A-related epilepsies present in most cases an autosomal dominant inheritance; however, there is growing evidence that some genetic variants only manifest clinical symptoms when they are present in both alleles, following an autosomal recessive inheritance." (PMID 34917021, 2021). "The relationship between the polymorphisms rs3812718 and rs2298771 of the SCN1A gene and the risk of CBZ resistance in epilepsy remains controversial." (PMID 34769124, 2021). "Mutations affecting three alpha subunit genes (SCN1A, SCN2A, and SCN8A) have been shown to cause epilepsies of variable severity." (PMID 34842787, 2021). "Genetic variants in the voltage-gated sodium channels SCN1A, SCN2A, SCN3A, and SCN8A are leading causes of epilepsy, developmental delay, and autism spectrum disorder." (PMID 34425903, 2021). "There was heterogeneity regarding causative genes (n = 754) with some of the most common ones being COL2A1 (n = 12; skeletal dysplasia), SCN1A (n = 8; epilepsy), and TNFRSF13B (n = 4; inborn errors of immunity)." (PMID 33726816, 2021). "We currently lack the ability to make in silico predictions about channel function from genetic data, limiting the current use of genetic insights in guiding treatment and prognosis for the heterogeneous SCN1A-related epilepsies." (PMID 34925043, 2021). "It is interesting to note that many of the ME-harboring epilepsy-associated genes are typically reported to be dysregulated in TLE patients’ brains, for example, SCN1A, BRD2, and NF1." (PMID 34868252, 2021). "In 73/293 (25%) patients, there was a treatment change prompted by the genetic diagnosis (16 of them also had PM trialled), but not directly related to known pathophysiological mechanisms (eg, valproate and stiripentol in SCN1A-related epilepsies)." (PMID 33903184, 2021). "For all epilepsy, GE and FE, SCN1A is the only gene that both (i) reaches genome-wide level of disease-significance, and (ii) produces a protein that is known to be altered in function by any existing compound." (PMID 34988442, 2021). "In this study, a meta-analysis was used to further explore the effects of SCN1A and SCN2A gene polymorphism on VPA response in children with epilepsy." (PMID 34011048, 2021). "In both mouse and fly knock-in models of SCN1A epilepsy, alterations in sodium currents and excitability have been primarily observed in inhibitory neurons." (PMID 34475263, 2021). "Advanced search was done using the following keyword combinations: SCN1A mutations in epilepsy, SCN1B mutations in epilepsy, SCN2A mutations in epilepsy, SCN3A mutations in epilepsy, SCN8A mutations in epilepsy and functional studies of VGSCs in epilepsy." (PMID 33841294, 2021). "Gabra2 repair restored transcript and protein expression, increased abundance of α2-containing GABAA receptors in hippocampal synapses, and rescued epilepsy phenotypes of Scn1a+/− mice." (PMID 34086081, 2021). "Monogenic epilepsies, such as Dravet Syndrome (SCN1A), provide additional insight into the heterogeneity of SUDEP mechanisms in paediatric epilepsy populations, as well as an opportunity to more precisely identify and treat individuals at increased risk." (PMID 34396109, 2021). "Sodium channel blockers have been avoided in SCN1A-related cases (loss-of-function variants) but preferred in early-onset SCN2A and SCN8A epilepsy (gain-of-function variants)." (PMID 33726816, 2021). "Our findings show that Scn1a 1b regulatory deletion mice represent a general epilepsy-relevant model that will be valuable for understanding the relationship between Scn1a dosage and neurological phenotypes in a genetic preclinical model." (PMID 33910599, 2021).
epilepsy (continued). "Although hyperexcitability in Scn1a epilepsy mouse models has been largely associated with impaired firing in inhibitory neurons, several studies suggest that excitatory neuronal firing could also be altered as seen in a human iPSC SCN1A model and an SCN2A mouse model." (PMID 33658306, 2021). "Variants in SCN1A and SCN2A have been linked to a spectrum of epilepsy phenotypes, including DS, generalised epilepsy with febrile seizures plus (GEFS+), WS and some other infantile epileptic disorders." (PMID 34163418, 2021). "Seizures induced by elevated temperature are characteristic of SCN1A—related epilepsies in general and DS in particular suggesting an overall net increase in excitatory to inhibitory balance." (PMID 34733140, 2021). "All controlled clinical trials on the association of SCN1A, rs3812718 and rs2298771 polymorphisms with CBZ resistance in epilepsy were included." (PMID 34769124, 2021). "The SCN1A IVS5-91G>A AA and ABCC2 c.1249G>A GA genotypes have been shown to be associated with carbamazepine/oxcarbamazepine-resistant epilepsy in the Chinese Han population." (PMID 32357528, 2020). "Here, we present two CRISPR/Cas9 generated knockout zebrafish models for SCN1A-related epilepsies, including Dravet syndrome." (PMID 32134913, 2020). "In vitro functional analysis is thus fundamental for elucidation of the molecular mechanisms of epilepsy, to guide patients’ treatment, and finally indicate misdiagnosis of SCN1A related epilepsies." (PMID 32581296, 2020). "We aimed to conduct a systematic review and meta-analysis to evaluate the association between SCN1A IVS5N+5 G>A polymorphism and risk of febrile seizures and epilepsy." (PMID 33391151, 2020). "Further to this, independent GWAS studies that show multiple significant associations between SNPs associated with SCN1A/SCN2A and epilepsy and/or febrile seizures, fail to do so for SCN9A." (PMID 33216760, 2020). "Several factors have been suggested to modify the clinical outcome of SCN1A‐related epilepsy and to explain these phenotypic differences." (PMID 32032478, 2020). "NaV1.1 (SCN1A), NaV1.2 (SCN2A), NaV1.3 (SCN3A), NaV1.6 (SCN8A) and NaV1.7 (SCN9A) are genes whose mutations are related to epilepsy." (PMID 33013363, 2020). "The SCN1A gene (MIM#182389), which is coded for the voltage-gated Na+ channel alpha subunit Nav1.1, is undeniably the most clinically relevant epilepsy gene with more than 1700 variants reported so far in various epilepsy phenotypes." (PMID 32581296, 2020). "This study aimed to determine the neuroprotective role of liraglutide in mouse and cell models of Scn1a KO-induced epilepsy." (PMID 32184723, 2020). "A wide variety of studies have confirmed the correlation between the down-regulation of SCN1A and epilepsy." (PMID 33244522, 2020). "In addition, there are numerous ways in which common genetic factors such as SCN1A mutations that predispose persons to the development of headaches and epilepsy and the corresponding mutations may result in higher prevalence of headaches among patients with epilepsy." (PMID 31924166, 2020). "Traditional VGSC blockers are known to be inefficient in SCN1A related epilepsies and can even sometimes aggravate seizures in Dravet syndrome, likely due to their limited NaV subtype specificity." (PMID 32134913, 2020). "Mutations in certain ion channel genes important for SCN function, such as SCN1A and KCNJ10, are well-known to strongly associate with epilepsy phenotypes in humans, and have served for many years as leads for AED development without great success." (PMID 32714261, 2020). "The gene whose variation appears to have the largest impact on the development of epilepsy is SCN1A, encoding Nav1.1, the major voltage-gated sodium channel expressed in CNS neurons." (PMID 32714261, 2020).
epilepsy (continued). "Four of them, in FOXP1, GRIN2B, SCN1A, and LAMC3 genes, were classified as potentially pathogenic and probably were associated with ASD, ID, and epilepsy." (PMID 30627967, 2019). "To date, a small number of gene mutations, such as in SCN1A and TSC2, are known to cause epilepsy and ASD phenotypes simultaneously." (PMID 31139143, 2019). "In the example, only SCN1A, DEPDC5 and GRIN2A are in the top 10 ‘epilepsy’ gene list both as genes with the most variants and most pathogenic variants." (PMID 31114901, 2019). "Based on previous evidence showing that heterozygous deletion mutations can give rise to severe forms of DS and since Scn1aΔE26 mice express Scn1a transcript, we expect Scn1aΔE26 mice to exhibit a mild epilepsy-like phenotype." (PMID 31025941, 2019). "Now, PCDH19 has become the second most relevant gene in epilepsy after SCN1A (Depienne & LeGuern, 2012; Duszyc, Terczynska, & Hoffman‐Zacharska, 2015)." (PMID 31714027, 2019). "Due to the aggressive epilepsy SCN1A was Sanger sequenced and this disclosed the novel splice variant NG_011906.1:g.76169G > C, (NM_001165963.2): c.4284 + 1G > C." (PMID 30305042, 2018). "Similar to the human variation in epilepsy severity, mouse models of SCN1A dysfunction, have been shown to have a strain dependent epilepsy phenotype, raising the possibility of additional factors contributing to pathogenesis." (PMID 29740280, 2018). "For example, a high incidence (at least 7%) of parental mosaicism has been detected by direct sequencing in families with inherited SCN1A-related epilepsies." (PMID 28837158, 2018). "Biological prioritization implicates SCN1A, SCN2A, SCN3A, and TTC21B as the most likely genes underlying the signal at 2q24.3 for all epilepsy, focal epilepsy and genetic generalized epilepsy." (PMID 30531953, 2018). "Mutations in SCN1A are also responsible for Genetic Epilepsy with Febrile Seizures Plus (GEFS+), which is an autosomal dominant form of epilepsy, typically less severe than DS." (PMID 29740280, 2018). "In this study, we evaluated the ability of SGE-516 to improve epilepsy phenotypes in the Scn1a+/− mouse model of Dravet syndrome." (PMID 29127345, 2017). "Mice with heterozygous deletion of Scn1a reproduce many DS phenotypes, including epilepsy with early onset, susceptibility to febrile seizures, sleep and circadian abnormalities, and premature death." (PMID 28812061, 2017). "In this study, we employ an extreme phenotype approach to search for genetic modifiers in a cohort of Japanese patients with SCN1A truncation-related epilepsy." (PMID 28686619, 2017). "In this study, we evaluated activity of SGE-516 on epilepsy phenotypes in the Scn1a+/− mouse model that recapitulates many features of Dravet syndrome, including spontaneous seizures, premature death and seizures triggered by hyperthermia." (PMID 29127345, 2017). "Overall, after the initial re-evaluation of the identified SCN1A HGMD variants, we suggest that only the p.T1174S variant is potentially a epilepsy associated variant." (PMID 26990884, 2016).
epilepsy (continued). "We further analyzed the family segregation pattern whereby a shared segregation of the SCN1A HGMD variant and epilepsy was evaluated as support for the variant pathogenicity." (PMID 26990884, 2016). "In particular, SCN1A alternative splicing has been extensively studied due to its relevance in CNS disorders such as epilepsy." (PMID 26503606, 2016). "To address the need for more efficacious treatments for SCN1A-derived epilepsies, we evaluated the therapeutic potential of Huperzine A, a naturally occurring reversible acetylcholinesterase inhibitor." (PMID 27799911, 2016). "Here we demonstrate significant decreases in metabolism in a zebrafish model of SCN1A-related epilepsy." (PMID 27066534, 2016). "In children with SCN1A-related epilepsies, seizure control is particularly critical as they are at high risk for sudden unexplained death in epilepsy." (PMID 27242528, 2016). "Other drugs, such as stiripentol, that have demonstrated clinical efficacy in the treatment of SCN1A-derived epilepsy have also been shown to increase resistance to hyperthermia-induced seizures in Scn1a rodent models." (PMID 27799911, 2016). "Taken together, our findings highlight the therapeutic potential of Huperzine A in increasing seizure resistance in SCN1A-derived epilepsy and potentially other forms of refractory epilepsy." (PMID 27799911, 2016). "The SCN1A gene, coding for the voltage-gated Na+ channel alpha subunit NaV1.1, is the clinically most relevant epilepsy gene." (PMID 26990884, 2016). "To investigate the effects of an epilepsy-causing VGSC mutation on sleep, we characterized the sleep/wake behavior of mutant flies harboring a knock-in SCN1A mutation (K1270T) that confers human GEFS+." (PMID 26361221, 2015). "Differential influence of genetic variants, namely SCN1A c.3184A>G and SCN1A IVS5-91, in epilepsy susceptibility and drug response have previously been reported." (PMID 26555147, 2015). "The differential SCN1A expression in rat myocardium might influence the susceptibility for sudden cardiac death in these children at different ages, since higher incidence of sudden death at young ages in patients with epilepsy has been described in multiple studies." (PMID 26542295, 2015). "In contrast with the RVIS method, the EvoTol approach identified SCN1A, an established epilepsy gene, as the most important gene in the Epi4K data set (0.04 percentile rank of evolutionary intolerance)." (PMID 25550428, 2015). "Of four risk loci identified for febrile seizures overall, two were in well-known epilepsy genes (SCN1A and SCN2A)." (PMID 26302787, 2015). "Mutations in other genes encoding ion channels, such as KCNQ2 in benign familial neonatal seizures and SCN1A in Dravet syndrome, led to the “channelopathy” hypothesis, which postulates that dysfunction or dysregulation of ion channels is a common mechanism underlying epilepsy syndromes." (PMID 26302787, 2015). "Meta-analysis of the all-epilepsy cohort identified loci at 2q24.3 (p=8·71 × 10−10), implicating SCN1A, and at 4p15.1 (p=5·44 × 10−9), harbouring PCDH7, which encodes a protocadherin molecule not previously implicated in epilepsy." (PMID 25087078, 2014). "Two patients with SCN1A truncation and severe cognitive decline presented with divergent epilepsy severity." (PMID 24225340, 2013). "Of these 13 children with SCN1A-related Dravet syndrome, eight had already been diagnosed with epilepsy at stage 1 of the study." (PMID 23762420, 2013). "Mutations in the SCN1A gene, previously linked to FHM and involved in several forms of epilepsy, would appear to be a rather unusual cause of HM." (PMID 24498617, 2013). "The SCN1A gene is a major gene in different epilepsies and epilepsy syndromes, and in this field it has to be further investigated." (PMID 21713554, 2011). "Our study seems to exclude a role of the SCN1A gene in the pathogenesis of migraine and in particular in cases with comorbidity between migraine and epilepsy." (PMID 21713554, 2011).
epilepsy (continued). "We exclude the role of the SCN1A gene in the pathogenesis of comorbidity between headache (especially migraine) and epilepsy." (PMID 21713554, 2011). "We excluded the role of the SCN1A gene in the pathogenesis of comorbidity between headache (especially migraine) and epilepsy." (PMID 21713554, 2011). "SCN1A is commonly mutated in Dravet syndrome and mutations in either SCN2A or SCN1A are associated with the generalized (genetic) epilepsy febrile seizure plus (GEFS+) syndrome." (PMID 19763161, 2009). "Our model adds to the growing list of other specific human epilepsy knockin mice, including the Gabrg2, Kcnq2, Kcnq3, Scn1a and Chrna4 mice, to report a clear-cut genotype to phenotype seizure susceptibility." (PMID 19763161, 2009). "Likewise, mutations in SCN1A, which codes for a voltage-gated sodium channel subunit, are associated with FHM type 3 and epilepsy." (PMID 40149800, 2025). "More recent studies, utilising broader genetic testing strategies, suggest that EAF may be more genetically heterogeneous, with causal variants in other epilepsy-associated genes also described, including DEPDC5 and SCN1A." (PMID 40381056, 2025). "Genetic models, such as SCN1A knockouts, have advanced knowledge of inherited epilepsies." (PMID 41333733, 2025). "We describe several genes-including CDKL5, TSC1/2, SCN1a, and TANC2-that have been associated with epilepsy, ASD, or other NDD phenotypes that play a critical role in regulating one or more stages of brain development or function but differ widely in their disease-causing mechanisms." (PMID 41594775, 2025). "Four children died during KD but none was assessed to be associated with the treatment (two in infections/pneumonia/sepsis, one in a postoperative complication not connected to KD and one in sudden unexpected death in epilepsy associated with SCN1A mutation)." (PMID 40290421, 2025). "For instance, adaptation of our approach into rare disease models of epilepsy, such as the Scn1a mouse model used to study Dravet Syndrome, could produce fresh insights into how seizures spread in different models." (PMID 39464023, 2025). "In the same way, several DEEs caused by mutations in CDKL5, DNM1, KCNT1, SCN1A, SCN2A, SCN8A, and UBA5 genes, which present severe pharmaco-resistant epilepsy, are increasingly becoming targets for RNA molecules that aim to restore neuronal excitability and network function." (PMID 41244709, 2025). "Furthermore, detailed determination of genotype–function–phenotype correlation is potentially useful for optimizing therapy in SCN1A‐related epilepsy." (PMID 39838578, 2025). "Emerging genetic research has identified mutations in genes such as SCN1A and PCDH19, which are associated with specific forms of epilepsy and may offer early diagnostic markers for high-risk children." (PMID 40809839, 2025). "None of the three patients with SCN1A variants had a clinical diagnosis of Dravet syndrome: two were seizure-free at 12 months (one of who was diagnosed with Genetic Epilepsy with Febrile Seizures Plus (GEFS+)), while the third continued to have seizures." (PMID 40399560, 2025). "Identifying specific pathogenic variants in genes such as SCN1A, SCN9A, and QARS1 and the recurrent combination of RANBP2 and RYR3 variants underscores the necessity for ongoing research to elucidate their roles in epilepsy development." (PMID 39509559, 2024). "Variations in SCN1A can result in a spectrum of hereditary seizure disorders." (PMID 38837984, 2024). "SCN1A rs3812718 and ABCC2 rs2273697 are associated with CBZ/OXC-resistant epilepsy." (PMID 39228521, 2024). "Compelling evidence indicates an important role for the SCN1A gene in the pathogenesis of epilepsy." (PMID 39336815, 2024). "SCN1A rs3812718 is associated with CBZ-resistant epilepsy but not the maximum or maintenance dose of CBZ." (PMID 39228521, 2024).